SLC16A3 (solute carrier family 16 member 3)
Diseases named in the same sentence as SLC16A3 in open-access papers (continued):
Sharing a sentence is not in itself a finding about the gene and the disease.
bladder cancer (3 papers, 2021 to 2024). "In this study, survival analysis of the transcriptome and the clinical data of bladder cancer patients in TCGA database showed that high SLC16A3 mRNA expression was associated with poor OS in patients with primary MIBC." (PMID 34513685, 2021). "In the present study, we first evaluated the expression of SLC16A3 mRNA in published single-cell RNA sequencing data of bladder cancer." (PMID 34513685, 2021). "In conclusion, our study revealed that SLC16A3 mRNA is upregulated in bladder cancer cells." (PMID 34513685, 2021). "The published single-cell RNA sequencing data of 49,869 bladder cancer cells and 15,827 normal bladder mucosa cells and The Cancer Genome Atlas (TCGA) bladder cancer cohort data were used to explore the mRNA expression of SLC16A3 in bladder cancer." (PMID 34513685, 2021). "Bladder cancer with high SLC16A3 mRNA expression has a poor OS." (PMID 34513685, 2021).
intrahepatic cholangiocarcinoma (3 papers, 2023 to 2025). A carcinoma that arises from the intrahepatic bile duct epithelium in any site of the intrahepatic biliary tree. "Because of the SLC16A3 gene mutation, it has been extensively studied in intrahepatic cholangiocarcinoma." (PMID 40301866, 2025). "SLC16A3 is a member of the solute carrier family and may be responsible for the export of lactate derived from glycolysis, which was further identified as a potential prognostic biomarker associated with intrahepatic cholangiocarcinoma." (PMID 38001569, 2023). "Although the relationship between SLC16A3 and cholestasis pathogenesis is unclear, recent research has identified this gene as a potential prognostic biomarker related to intrahepatic cholangiocarcinoma cell reprogramming." (PMID 37603094, 2023).
liver cancer (3 papers, 2017 to 2024). An epithelial or non-epithelial malignant neoplasm that arises from the liver. "To investigate the role of SLC16A3 in the immune microenvironment, we collected additional single‐cell data from 10 primary liver cancer patients." (PMID 39656344, 2024). "This indicated that under conditions of low SLC16A3 expression, the liver cancer microenvironment had the potential for enhancing immune response activation." (PMID 39656344, 2024). "SLC16A3, belonging to the proton-linked monocarboxylate transporter (MCT) family, was significantly up-regulated in liver cancer in multiple datasets and in our study." (PMID 30463528, 2018). "Among these genes, PCOLCE and ZBTB16 were significantly down-regulated, while SLC16A3 was significantly upregulated in liver cancer." (PMID 28740751, 2017). "DAPK1 expression was positively correlated with IRF2, IL7R, PCOLCE and ZBTB16, and negatively correlated with SLC16A3 in both liver cancer datasets." (PMID 28740751, 2017). "These survival curves indicated that overexpression of SLC16A3 might lead to unfavourable prognosis in liver cancer patients." (PMID 39656344, 2024). "This underscores the pivotal role of SLC16A3 within the tumour microenvironment of liver cancer." (PMID 39656344, 2024). "In the current study, we have also identified few genes that are co-regulated with DAPK1, especially for SLC16A3, PCOLCE and ZBTB16, since the expression of these genes were dysregulated in liver cancer." (PMID 28740751, 2017).
renal carcinoma (3 papers, 2016 to 2025). A carcinoma arising from the epithelium of the renal parenchyma or the renal pelvis. "Recent studies have validated the upregulation of SLC16A3 in lung, breast, and renal cancers, suggesting its potential oncogenic role in these cancers." (PMID 40301866, 2025). "NNMT, PLOD2, HAPLN3, PLIN2, and SLC16A3 showed medium to strong tumor-specific staining in more than 90% renal cancer samples, indicating higher general applicability of these biomarkers." (PMID 35440542, 2022). "For example, MDM2, SLC16A3, LFT etc. show expression change in renal cancer; SLC22A7, ACHE, BMP4 etc. are associated with renal function." (PMID 27258182, 2016).
Alzheimer disease (2 papers, 2023 to 2025). A progressive, neurodegenerative disease characterized by loss of function and death of nerve cells in several areas of the brain leading to loss of cognitive function such as memory and language. "The two identified microglial aging genes, P2ry13 and Slc16a3, are also found to be down- and up-regulated, respectively, in the so-called disease-associated microglia (DAM) that are found in Alzheimer’s disease as well as other neurodegenerative disorders." (PMID 39828750, 2025). "Hence, further studies in vitro and in vivo of intron 2 retention in the Slc16a3 gene transcript are required for adequate characterization concerning the biological roles of Slc16a3 isoforms in the context of aging and Alzheimer’s disease pathology." (PMID 37895298, 2023).
colon carcinoma (2 papers, 2021 to 2022). "Since the expression levels of CTHRC1, FBN2, NTM, PDGFC, PDLIM3, and SLC16A3 are significantly differentiated among the normal samples, primary tumor, and metastatic tumor, we anticipated that these genes are associated with metastasis in colon cancer." (PMID 35991839, 2022). "We found that upregulated group of CTHRC1, NTM, PDGFC, PDLIM3, and SLC16A3 genes are consistently correlated with the shorter survival of colon cancer patients in GSE17536." (PMID 35991839, 2022). "Studies have shown that hypoxia-inducible factor-1 (HIF-1) can enhance the transcription of SLC16A3, thereby enhancing the proliferation of colon cancer." (PMID 34424811, 2021). "Finally, we investigated the correlation of CTHRC1, FBN2, NTM, PDGFC, PDLIM3, and SLC16A3 with the metastatic scores in colon cancer data." (PMID 35991839, 2022). "Since the upregulated group of CTHRC1, NTM, PDGFC, PDLIM3, and SLC16A3 and the downregulated group of FBN2 genes are consistently correlated with the shorter survival time in TCGA and GEO datasets, we investigated the association of these genes with immune score and stromal scores in colon cancer." (PMID 35991839, 2022). "The upregulation of CTHRC1, PDGFC, PDLIM3, NTM, and SLC16A3 and downregulation of FBN2 are correlated with a shorter survival time in colon cancer." (PMID 35991839, 2022). "However, the expression levels of PDLIM3 and SLC16A3 are not significantly altered in colon tumor stroma (p < 0.05) and the expression level of FBN2 showed the opposite trend in the high-CAFs group." (PMID 35991839, 2022).
colorectal cancer (2 papers, 2022 to 2023). A primary or metastatic malignant neoplasm that affects the colon or rectum. "Hypermethylation of the SLC16A3 promoter leads to reduced MCT4 expression in colorectal carcinoma." (PMID 37816756, 2023).
rheumatoid arthritis (2 papers, 2022 to 2023). A chronic, systemic autoimmune disorder characterized by inflammation in the synovial membranes and articular surfaces. "This includes cases where SLC16A3 has been suggested as possible target in disease areas such as cancer or rheumatoid arthritis." (PMID 37516113, 2023). "From single‐cell RNA‐sequencing analysis of synovial tissues isolated from rheumatoid arthritis patients, we identified that the expression of SLC2A1 and SLC16A3 increased along with concentrations of proinflammatory factors and glycolytic enzymes." (PMID 36354099, 2022).
astrocytomas (1 paper, 2020). "GBM exhibited increased expression levels of the MCT genes SLC16A1 and SLC16A3 when compared to normal brain parenchyma, as well as oligodendrogliomas and astrocytomas." (PMID 32045997, 2020).
cholestasis (1 paper, 2023). Impairment of the bile flow caused by obstruction within the liver, or outside the liver in the bile duct system. "The putative functions of two less investigated genes (i.e., SLC16A3 and VSIG10L) were found to correlate with previously discovered key events involved in the development of cholestasis, specifically bile flow disruption, and autophagy." (PMID 37603094, 2023).
colon adenocarcinoma (1 paper, 2025). "Nevertheless, no considerable variance was noted in the SLC16A3 expression relative to the adjacent healthy tissues of colon adenocarcinoma (COAD) and rectum adenocarcinoma (READ)." (PMID 40301866, 2025).
diabetes (1 paper, 2013). "The remaining non-calcium ion channel genes in the sternohyoid, Slc16a3, Amy1a, Chrnd and Ltbp1 did not have changed expression in previous studies of diabetes." (PMID 24199937, 2013).
disc degeneration (1 paper, 2024). "This theme also highlighted the downregulation of Slc16a3, or MCT4, a plasma-membrane monocarboxylate which is essential to maintain a balance between glycolytic and TCA cycle flux as its inhibition leads to disc degeneration." (PMID 38510179, 2024).
kidney cancer (1 paper, 2020). Primary or metastatic malignant neoplasm involving the kidney. "SLC16A3 DNA methylation and MCT4 protein levels were found to be prognostic markers for kidney cancer and thyroid cancer." (PMID 32355273, 2020).
lactic acidosis (1 paper, 2023). Metabolic acidosis characterized by the accumulation of lactate in the body. "Macrophages appear to be more reliant on glycolytic metabolism and respond to high level of lactate by upregulating SLC16A3 in order to prevent intracellular lactic acidosis and cell death." (PMID 37304267, 2023).
metastatic tumor (1 paper, 2022). "Interestingly, we found that CTHRC1, NTM, PDGFC, PDLIM3, and SLC16A3 are gradually upregulated from normal to a metastatic tumor, indicating the association of these genes in tumor progression (Welch’s t-test, p < 0.05)." (PMID 35991839, 2022). "Moreover, the CTHRC1, PDGFC, PDLIM3, NTM, and SLC16A3 genes are gradually increased from normal tissue to the tumor and tumor to the metastatic tumor, and FBN2 showed the reverse pattern." (PMID 35991839, 2022).
osteoarthritis (1 paper, 2021). A noninflammatory degenerative joint disease occurring chiefly in older persons, characterized by degeneration of the articular cartilage, hypertrophy of bone at the margins and changes in the synovial membrane. "Also, SLC16A3 (MCT4) transcripts were up-regulated in synovial fibroblasts from rheumatoid arthritis patients compared with osteoarthritis patients, and knockdown of SLC16A3 (MCT4) prevented their proliferation." (PMID 34492096, 2021).
Parkinson disease (1 paper, 2020). A progressive degenerative disorder of the central nervous system characterized by loss of dopamine producing neurons in the substantia nigra and the presence of Lewy bodies in the substantia nigra and locus coeruleus. "We evaluated the recent literature on candidate blood biomarkers in Parkinson’s disease patients and observed five differentially methylated genes (COL9A2, SCNN1A, AMICA1, SLC16A3, and DLK1) in these studies within our conserved human regions." (PMID 32178731, 2020).
polycystic kidneys (1 paper, 2018). "Compared with wild-type mice, Pkd1 miR Tg mice had significantly higher levels of Slc16a3 and Hk2 mRNA expression, indicating an increase in glycolytic activities in polycystic kidneys." (PMID 30585217, 2018).
postpartum hemorrhage (1 paper, 2022). Hemorrhage defined as a blood loss in excess of 500 mL after vaginal delivery or more than 1000 mL after a cesarean delivery. "Eight genes were associated with hemostatic pathways (SELL, CAPZB, SLC16A3, PDPN, TNFRSF10B, SH2B2, NFE2, and TNFRSF10D), which provided novel insights for the prevention and management of postpartum hemorrhage." (PMID 35836580, 2022).
schizophrenia (1 paper, 2024). A major psychotic disorder characterized by abnormalities in the perception or expression of reality. "In the lactate shuttle, six (55%) of the significantly altered genes (n = 11) were upregulated: GLUL, LDHC, SLC16A3, SLC1A2, SLC1A3, and SLC2A1, which were collectively expressed in schizophrenia groups at a level of 1.5× higher than in control groups (LFC = 0.58)." (PMID 39125835, 2024).
Sepsis (1 paper, 2020). Sepsis is defined as life-threatening organ dysfunction caused by a dysregulated host response to infection. "It associates directly with TDRD9 and indirectly with SLC16A3 in pediatric sepsis, through MTF1, CD82, and G6PD." (PMID 32318053, 2020). "Amongst the clusters in the maps, cluster MYL9, GPR84, and SLC16A3 showed uni- and/or bi-stimulatory signals in most groups, with the exception of adult sepsis which exhibited inhibitory signals." (PMID 32318053, 2020). "SLC16A3 [solute carrier family 16 (monocarboxylic acid transporters), member 3], showed no increased interaction between the hubs in any of the disease states except pediatric sepsis compared with healthy controls." (PMID 32318053, 2020). "Gene entities shared between sepsis and severe sepsis response hubs are; TDRD9 – LIN7A, GPR84 – ENTPD7, PYCT1A and ZDHHC19, CD177 – DDAH2 and RGL4, SLC16A3 – DENND3 and MBD6, MYL9 – CMTM5, ITGB3, ITGA2B, NRGN, SELP and TREML1." (PMID 32318053, 2020). "The pattern is similar to that for pediatric sepsis with connections between nearly all hubs with the exception of KLRK1, SLC16A3, and MYL9." (PMID 32318053, 2020). "The majority of these clusters were not connected in most disease and control states, except for adult sepsis and adult SIRS with the gene clusters for TDRD9, CD177, GPR84, PCOLCE2, FGF13 and SLC16A3 interconnected at various points, either directly or through overlapped gene connections." (PMID 32318053, 2020).
septic arthritis (1 paper, 2022). "As the physiological symptoms of septic arthritis worsened with greater MRSA bioburden, the mRNA expression of Slc2a1 and Slc16a3 increased, and expression levels slightly decreased over time, but still remained higher than normal." (PMID 36354099, 2022).
synovitis (1 paper, 2023). Inflammation of a synovial membrane. "SLC16A3 mRNA expression positively correlated with the histological grade of synovitis (CD3, CD20, CD69 and CD138 infiltration) and the disease activity score (DAS28 ESR and CRP)." (PMID 37304267, 2023).
tongue cancer (1 paper, 2012). A malignant neoplasm affecting the tongue. "Four novel genes of potential importance in tongue cancer development and maintenance, SH3BGL2, SLC2A6, SLC16A3 and CXCL10, were independently confirmed, validating our data." (PMID 22530001, 2012).
Type 1 Diabetes (1 paper, 2024). "We found GWAS links between 7 T2D-DMP genes and T2D or related phenotypes, including SPRED2 (T2D), ITPR1 and PLD6 (Diabetic complications), SLC16A3 (BMI), TCF7 (Type 1 Diabetes), RGL3 (blood pressure) and TNIP1 (autoimmune traits)." (PMID 38574408, 2024).
tumor (76 papers, 2005 to 2025). "In LIHC, LUAD, OSCC, and PAAD, the expression of SLC16A3 was linked to the tumor stage (pathologic stage and clinical stage)." (PMID 40301866, 2025). "Future investigations should focus on exploring underlying mechanisms to uncover the pivotal role of SLC16A3 in regulating the metabolic reprogramming of the tumour microenvironment." (PMID 39656344, 2024). "Increased SLC16A3 expression in cancer cells causes accumulation of lactate in the tumor microenvironment, which results in an acidic pH." (PMID 37775731, 2023). "Therefore, these three key MVIRGs (DBF4, ARG2, and SLC16A3) are closely associated with the tumor and its prognosis, which also proves the correctness of choosing these three MVIRGs to establish a prognostic model to a certain extent." (PMID 34975331, 2022). "Analysis of transcriptomic data from TCGA LUAD cohort revealed that SLC16A3 expression was significantly upregulated in tumor tissues compared to that in adjacent normal tissues." (PMID 41293164, 2025). "In preclinical studies, ALK-04 demonstrated significant therapeutic potential by synergistically reducing melanoma tumor growth when combined with GVAX/anti-PD-1 immunotherapy via MCT4/SLC16A3 axis." (PMID 40823087, 2025). "SLC16A family members play important roles in tumorigenesis, nonetheless, the specific involvement of SLC16A3 in tumor prognosis and diagnosis in human cancers remains unelucidated." (PMID 40301866, 2025). "Tumor models demonstrate that SLC16A3 overexpression enhances lactate export, while its inhibition suppresses the Warburg metabolism." (PMID 41377071, 2025). "SLC16A3 knockdown suppressed tumor cell growth and enhanced ferroptosis, as indicated by increased lipid peroxidation, iron accumulation, and mitochondrial depolarization." (PMID 41293164, 2025). "Next, an analysis of SLC16A3 expression across 33 tumor types, in comparison to healthy tissues, was conducted using data from the TCGA and GTEx databases." (PMID 40301866, 2025). "SLC16A1 (classically named monocarboxylate transporter 1, MCT1) and SLC16A3 (MCT4) are the relevant isoforms that basically carry the full load of monocarboxylate transport in tumor cells." (PMID 40508207, 2025). "In vivo xenograft assays using BALB/c nude mice demonstrated that SLC16A3 knockdown markedly reduced tumor growth, as evidenced by the reduced tumor weight and volume over time." (PMID 41293164, 2025). "We identified a metabolic‐related gene, SLC16A3, that significantly influences the tumour microenvironment." (PMID 39656344, 2024). "Inhibiting SLC16A3 suppresses glycolysis and lactate efflux, thereby enhancing T cell-mediated tumor responses and improving outcomes with anti-PD-1 therapy." (PMID 39461979, 2024). "Single‐cell analysis showed that the SLC16A3 gene was mainly expressed in macrophages, especially some tumour‐promoting macrophages." (PMID 39656344, 2024). "Overall, our study identified a metabolic‐related gene, SLC16A3, which correlated with the tumour microenvironment, providing insights into the interplay between SLC16A3 and the immune landscape within HCC." (PMID 39656344, 2024). "Further analysis of spatial transcriptome data indicated that SLC16A3 was enriched at the tumour invasion front." (PMID 39656344, 2024). "Differential analysis indicated that SLC16A3+ macrophages exhibit high expression of macrophage markers promoting migration, invasion and tumour angiogenesis, such as SPP1 and MMP9, as well as genes associated with glycolysis, including PKM." (PMID 39656344, 2024). "In this study, expression of LDHA and SLC16A3 was significantly higher in the EGFRHIGH/METHIGH subcluster of HNSCC PDX tumor compared to the EGFRLOW/METLOW subcluster (P < 0.05)." (PMID 38916448, 2024). "ALKBH5-KO B16 tumors exhibited reduced expression of Mct4/Slc16a3, lactate content in the tumor-infiltrating fluid (TIF), and decreased abundance of myeloid-derived suppressor cells (MDSCs) and regulatory T cells (Tregs) within TME." (PMID 39199429, 2024).